EPHB4 (EPH receptor B4)
Diseases named in the same sentence as EPHB4 in open-access papers (continued):
Sharing a sentence is not in itself a finding about the gene and the disease.
tumor (continued). "We found that the antiproliferative activity of HHT in HCC cells and tumor xenograft was closely related to EphB4 expression." (PMID 32801343, 2020). "HHT has an enhanced inhibitory effect on EphB4+/7721 tumor growth compared with that on wild type 7721 tumor." (PMID 32801343, 2020). "Activated by its corresponding ligand EphrinB2, EphB4 controls cell–cell interactions, angiogenesis, tumor growth, and metastasis." (PMID 32801343, 2020). "Both mRNA and protein analysis revealed that the EphB4 is overexpressed in all CRLCs from tumor samples tested compared with normal human bronchial epithelial cells." (PMID 32733636, 2020). "Another study showed that EphB4 suppresses sprouting angiogenesis and induces circumferential growth of blood vessels in tumor xenografts." (PMID 33614496, 2020). "Our previous study has confirmed the overexpression of EphB4 in the tumor tissues of HCC patients, emphasizing EphB4 a potential target for HCC treatment." (PMID 32801343, 2020). "Two independent tissue micro arrays, consisting of matched sets of tumor and normal breast tissue, were stained for EphB4 by immunohistochemistry." (PMID 32751634, 2020). "EphB4 would promote the tumor angiogenesis by interacting with ephrin-B2 expressed on tumor vasculature." (PMID 32316101, 2020). "The present study adds new evidence that NVP is able to reverse shPDCD10-induced activation of EphB4 thus its tumor-promoting effect via inhibiting EphB4 in GBM cells and in a mouse model of human GBM." (PMID 32850441, 2020). "Immunofluorescence co-localization analysis showed that EphB4 was expressed in both tumor vasculature and tumor cells in the MDA-HGSC-1 PDX model." (PMID 31949258, 2020). "EphB4 would seem to protect from the innate tumor necrosis factor-induced apoptosis and to support the tumor growth." (PMID 32316101, 2020). "EphB4 is an important member of the receptor tyrosine kinase family which is overexpressed and conduces to tumor growth and migration in various cancers." (PMID 32801343, 2020). "For example, EFNB2-Fc–mediated EphB4 phosphorylation activated Abl family tyrosine kinase and Crk adaptor protein in tumor cells, which led to significant tumor-suppressive activity." (PMID 31949258, 2020). "This switch in the expression of EphB4 and EphB2 would provide survival advantages to tumor cells during tumor progression." (PMID 32316101, 2020). "EPHB4 plays a crucial role in cardiovascular development and regulates vascularization in cancer‐promoting angiogenesis, tumour growth and metastasis." (PMID 32336043, 2020). "Nude mice injected with HT-29 cells, a line of human adenocarcinoma, showed reduced tumor growth and tumor angiogenesis after EphB4 suppression." (PMID 32316101, 2020). "In the 39 paired samples (T/N) the mean score for EphB4 staining was 4.8 ± 1.7 in tumor tissue versus 4.0 ± 1.5 in normal tissue." (PMID 32751634, 2020). "This revealed prominent tumor accumulation of mAb47 compared to an IgG control, which, as it binds to both human and mouse EphB4, suggests specificity for tumor over normal tissues." (PMID 32397088, 2020). "The tyrosine kinase receptor EphB4 is frequently overexpressed in ovarian and other solid tumors and is involved in interactions between tumor cells and the tumor microenvironment, contributing to metastasis." (PMID 31949258, 2020). "A paired t-test confirmed the difference in EphB4 between tumor and normal tissue, with a p-value of 0.03." (PMID 32751634, 2020). "In summary, our studies provide comprehensive evidence to support the use of BIDEN-AP for targeting bi-directional EphB4/EFNB2 signaling to reduce tumor growth and metastasis and to overcome resistance to antiangiogenic therapy." (PMID 31949258, 2020). "Others have developed near infrared florescence probes with EphB4 antibodies for targeted tumor imaging." (PMID 32751634, 2020).
tumor (continued). "More importantly, the treatment with NVP not only abolished PDCD10-knockdown-mediated activation of EphB4, but also suppressed the aggressive tumor progression and rapid growth in shPDCD10 mice." (PMID 32850441, 2020). "Specifically, EPHB4 inhibition impairs tumor cell metabolism though changes in glucose transporter and glucose uptake, resulting in ER stress and immunogenic cell death." (PMID 31641103, 2019). "Previous studies have shown that EPHB4 promotes tumor cell survival and is overexpressed in prostate cancer." (PMID 31641103, 2019). "As shown, the relative levels of tyrosine‐phosphorylated EphB4 were significantly lower in HT‐29 tumor extracts from NVP‐Iso‐treated mice compared to controls, but residual tyrosine phosphorylation was detected despite treatment." (PMID 31545551, 2019). "In the tumor microenvironment, upregulation of ephrin-A2, ephrin-A3, EphB2, and EphB4, to name a few, on vascular cells in response to tumor factors has been the most well-studied." (PMID 31333644, 2019). "In this regard, EphB4 has been shown to exert tumor progressive effects in the case of EphB4 overproduction in a ligand-independent mechanism, while ligand-dependent stimulation acts tumor suppressive." (PMID 29987450, 2018). "Quantification of Hoechst 33342- and CD31-positive tumor area confirmed a reduced amount of (functional) blood vessels in A375 EphB4 tumors in comparison to mock tumors." (PMID 29462967, 2018). "We observed that inhibition of EphB4-ephrin-B2 signaling in vivo significantly reduced tumor growth and decreased the infiltration of Tregs, TAMs, and increased infiltration and activation of Teffector cells, without affecting CD4 T cell numbers." (PMID 30400822, 2018). "The influence of EphB4 on tumor growth in experimental studies is contradictory and seems to be highly dependent on the cellular context, especially on co-expression of its preferred ligand EphrinB2." (PMID 29462967, 2018). "Our study provides the first insight into a novel role for EphB4-ephrin-B2 interaction in modulating tumor immune microenvironment in HNSCC." (PMID 30400822, 2018). "Our data demonstrated that combining EphB4-ephrin-B2 inhibitor with RT was equally effective to that of anti-PDL1+RT in terms of anti-tumor growth response." (PMID 30400822, 2018). "Patients with low ephrin type-B receptor 4 (EPHB4) mRNA levels in tumor tissue have a higher response to B than those with high levels." (PMID 28465540, 2017). "In this work, we test a possibility of using flexible docking of a short linear motif to predict the interaction interface of the EphB4-EphrinB2 complex (a system extensively studied for its significance in tumor progression)." (PMID 28830442, 2017). "A previous study reported that EphB4 is an important indicator of poorly differentiated hepatocarcinoma, with EphB4 expression correlating with angiogenesis and tumor progression." (PMID 29207612, 2017). "In a preliminary evaluation on five sets of tumor and normal tissue sections, two different antibodies recognizing EphA2 and two different antibodies recognizing EphB4 showed similar staining patterns." (PMID 28165374, 2017). "Our IHC evaluation of 168 sets of N/T tissue showed a statistical significant upregulation in tumor tissue compared with normal tissue for both EphA2 and EphB4 in the majority of the patients." (PMID 28165374, 2017). "Next, we found that the expression of EphB4 in tumor tissues was also decreased in the combination treatment group compared with the other treatment groups." (PMID 29207612, 2017). "The signaling effects of EphA2 and EphB4 in cancer are complex, and not only tumor-promoting but also tumor-suppressing effects have been reported for these receptors." (PMID 28165374, 2017). "In support of this, a recent study has shown that the combination of DLL4‐Notch and EphrinB2/EphB4 targeted therapy is highly effective in disrupting tumour angiogenesis." (PMID 28371279, 2017).
tumor (continued). "The results show a significantly enhanced staining intensity and more widespread distribution in tumor tissue compared with adjacent normal tissue for EphA2 as well as EphB4." (PMID 28165374, 2017). "Previous studies reported that EphB4 overexpressed in HNSCC cells promoted tumor development by stimulating angiogenesis, increasing cancer cell survival, and facilitating invasion and migration." (PMID 29190834, 2017). "For photothermal-combined cancer chemotherapy, orthotopic and subcutaneous xenograft clone tumor models with EphB4-positive expression were successfully generated." (PMID 28942682, 2017). "The biodistribution study in mice bearing an EphB4-positive tumor on one side and an EphB4-negative tumor the other side also indicated significantly more retention of the micelles in the tumors with high EphB4 expression." (PMID 28942682, 2017). "In this study, we evaluate the expression patterns of EphA2 and EphB4 by immunohistochemical (IHC) staining of a tissue microarray (TMA) consisting of pairs of tumor and normal colon tissue." (PMID 28165374, 2017). "To address the in vivo role of EphB4 inhibition in eRMS tumor progression, we utilized the EphB4 inhibitory antibody, VasG3, in an eRMS patient-derived xenograft (PDX) model." (PMID 28817624, 2017). "As seen in in vitro co-culture studies, EphA2, EphB2 and EphB4 phosphorylation was reduced in whole tumour lysates of Tie2PEKO animals, independently of changes in gene expression." (PMID 28719590, 2017). "Previously, we demonstrated that inhibition of EphB4 signaling in a murine aRMS allograft model using dasatinib, a receptor tyrosine kinase and Src kinase inhibitor, effectively decreased tumor progression." (PMID 28817624, 2017). "Our evidence suggests that Dll4/Notch signaling amplification stabilizes tumor vessels by enhancing EphrinB2/EphB4 and PDGF/ PDGFRβ signaling and, therefore, promoting vascular maturation." (PMID 28288569, 2017). "Staining for EphA2 and EphB4 was generally present in epithelial cells throughout the whole tumor area consisting of 2 or 3 TMA cores." (PMID 28165374, 2017). "Previous studies showed that overexpression of EphB4 involves in tumor progression by promoting angiogenesis, increasing survival, and promoting invasion and migration." (PMID 28194092, 2017). "PCB380 is a patient-derived primary aRMS tumor while Rh30 is a human aRMS cell line, both of which express both EphB4 and EphrinB2 proteins." (PMID 28817624, 2017). "In this context, EphB receptors are expressed as Wnt targets, with EphB2 characterized as a tumor suppressor to constrain tumor growth in ApcMin/+ mice, whereas EphB4 promotes cancer progression." (PMID 27589803, 2016). "EphB4-ECD-HSA can also have inhibitory effects on some tumour cells and has led to complete remission in bladder cancer xenografts with bevacizumab treatment." (PMID 26620208, 2016). "In tumour angiogenesis the expression of EphB4 on tumour cells has been shown to be important in interacting with ephrinB2 on ECs and promoting tumour angiogenesis." (PMID 26620208, 2016). "In CUHN022 tumor, radiosensitization due to EphB4 targeting was observed after radiation dose de-escalation." (PMID 27941840, 2016). "Our findings suggest that the DNA damage response pathway stimulated in response to EphB4 knockdown and radiation ultimately results in tumor cell death." (PMID 27941840, 2016). "The combination of radiation and EphB4 targeting used not only resulted in a significant reduction in tumor volume but also delayed tumor growth compared to single agent treatments." (PMID 27941840, 2016). "No inhibitory Ab response was seen, even after 65 h in culture, indicating that one or more of the peptides was binding to the functional Ab in the polyclonal mix and preventing attachment to the native EphB4 protein expressed on the tumour cell surface." (PMID 25831049, 2015).
tumor (continued). "MAb131 can induce EphB4 degradation and inhibits endothelial tube formation in vitro and also inhibits the growth of EphB4-positive tumour xenografts." (PMID 25831049, 2015). "Addition of antibody to cancer cells resulted in phosphorylation and subsequent degradation of the EphB4 protein, suggesting a mechanism that is ligand mimetic and tumour suppressive." (PMID 25831049, 2015). "Soluble monomeric EphB4 can block tumour angiogenesis and is being explored as anti-tumour therapeutics." (PMID 25831049, 2015). "To date, EphB4 has been shown to be over-expressed in 1046 of 1318 (82%) individual tumour samples from a wide selection of epithelial cancers." (PMID 25831049, 2015). "The critical importance of EphB4 in tumour progression is demonstrated by studies using over-expression and knockdown strategies." (PMID 25831049, 2015). "Combining the data from these studies, currently to date, EphB4 protein levels have been tested in 1318 individual tumour samples and is increased above the level in normal matched tissues in 1046 (82%) of these." (PMID 25831049, 2015). "These suggest that EphB4 signaling blockade leads to inhibited tumor angiogenesis and tumor cell proliferation and also induced tumor cell apoptosis." (PMID 25148033, 2014). "Summary of immunofluorescence staining analysis of EphB4 and EphB2 expression in normal and tumor urothelium specimens." (PMID 25148033, 2014). "The switch from EphB2 to EphB4 from normal bladder to tumor remains a prominent finding based on two orthogonal methods." (PMID 25148033, 2014). "As expected, sEphB4-HSA markedly reduced EphB4 phosphorylation, indicating sEphB4-HSA gained access to EphB4 expressing on tumor cells and inhibited EphB4 signaling in vivo." (PMID 25148033, 2014). "If this is the case, targeting EphB4 would kill tumor cells and spare normal bladder and thus lack toxicity." (PMID 25148033, 2014). "The clinical and pathologic characteristics of the 34 patients in which tumor specimens were received were also examined and correlated with EphB4 signal strength." (PMID 25148033, 2014). "Patient survival was strongly positively correlated with tumor expression of EphB4, as those with high EphB4 expression have a median survival threefold longer than those with low expression (51 months versus 17 months, p = 0.021)." (PMID 23844053, 2013). "EphB4 activation leads to downstream activation of the phosphoinositide kinase-3 (PI3K) pathway in tumor cells, while Ephrin-B2 activation leads to activation of Src." (PMID 23721559, 2013). "We show that a significant proportion of MPM tumors expressed EphB4, which provides survival advantage to tumor cells." (PMID 23721559, 2013). "Overall, the pattern of overexpression observed here in lung tumors was remarkable, and it is perhaps related to the gene copy number findings, in which a subset of tumor tissues were found to have increased EPHB4 gene copy numbers." (PMID 23844053, 2013). "The effects of EphB4 inhibition with sEphB4-HSA were investigated using mouse tumor xenograft models." (PMID 23844053, 2013). "Contrastingly, the findings based on tumors revealed that EphB4 is located on the tumor cell surface." (PMID 23596494, 2013). "The EphB4 inhibitor sEphB4-HSA was highly active as a single agent to inhibit tumor growth, accompanied by tumor cell apoptosis and inhibition of PI3K and Src signaling." (PMID 23721559, 2013). "Although the role of Eph receptors in cancer progression is complex, and EphB4 has been shown to have tumour promoting and inhibitory functions, EphB4 is generally thought to convey a more invasive phenotype." (PMID 23495724, 2013). "Inhibition of EphB4-Ephrin-B2 signaling blocks tumor angiogenesis, which in turn leads to hypoxia and induces VEGF expression." (PMID 23721559, 2013). "Inhibition of their interaction by EphB4 antibody or extracellular fragment of EphB4 can inhibit tumor angiogenesis and tumor growth." (PMID 22292016, 2012).
tumor (continued). "Antibodies against EphB4 were found to inhibit tumor growth and angiogenesis, some of which are being investigated for anti-cancer therapy in preclinical studies." (PMID 22292016, 2012). "Targeting the ephrin-ephrin receptor interactions by antibodies, siRNA, or soluble ligands (e.g soluble EphB4, the receptor for ephrin-B2, fused to albumin) disrupts endothelial cell function and tumor vasculature." (PMID 23209418, 2012). "Soluble extracellular domain of EphB4 targeting ephrin-B2 has been used in inhibiting angiogenesis and tumor growth in vivo." (PMID 22292016, 2012). "Specific antibodies to EphB4, soluble EphB4 or small molecule inhibitors reduced tumor angiogenesis." (PMID 24213317, 2012). "Ephrin-B2 is critical for the survival of KS tumor cells, while EphB4 is downregulated upon KSHV infection." (PMID 23209418, 2012). "In fact, several studies highlighted an important role forEphA2-ephrinA1 and EphB4-ephrinB2 interaction in tumor angiogenesis." (PMID 21479221, 2011). "Particular attention should be paid to expression profiles in tumor endothelium, given the role of B class receptors like EphB4 in angiogenesis and tumor neovascularization, as well as vessel maturation and vascular integrity." (PMID 21935409, 2011). "The interaction between EphB4 expressed in circulating tumor cells and ephrin-B2 expressed in endothelial cells has also been reported to mediate site-specific metastatic dissemination." (PMID 22194865, 2011). "EphB4-ephrin-B2 interaction is also known to play a critical role in angiogenesis, including blood vessel remodeling during embryonic development, tumor vascularization and other forms of pathological angiogenesis." (PMID 22194865, 2011). "Dll4/Notch and Ephrin-B2/EphB4 pathways play critical roles in tumor vessel development and maturation." (PMID 21092311, 2010). "The monomeric form of the extracellular domain of EphB4 functions as an antagonist of EphB4-Ephrin-B2 signaling, thus blocking endothelial cell migration, tube formation and retards angiogenesis in tumor models." (PMID 21092311, 2010). "Beyond tumor pathology, soluble ephrinB2-Fc or EphB4-Fc chimeras, respectively, and soluble ephrinB2 were shown to reduce pathologic neovascularization in the retina." (PMID 20224755, 2010). "sEphB4-Alb has been shown to be a potent inhibitor of tumor angiogenesis by blocking Ephrin-B2 and EphB4 signaling." (PMID 21092311, 2010). "In summary, targeting of Dll4/Notch and Ephrin-B2/EphB4 in combination showed marked improvement in tumor growth inhibition." (PMID 21092311, 2010). "The importance of EphB4/ephrinB2 in tumor angiogenesis and tumor growth was also demonstrated in recent work on mouse models." (PMID 20224755, 2010). "We sought to determine the effect of combined blockade of Dll4/Notch pathway (by sDll4) and Ephrin-B2/EphB4 pathway (by sEphB4-Alb) on tumor angiogenesis." (PMID 21092311, 2010). "The soluble EphB4 instead reduced vessel density and vessel perfusion, leading to reduction of tumor size." (PMID 21092311, 2010). "sEphB4-Alb mediated inhibition of Ephrin-B2/EphB4 signaling also results in areas of hypoxia in the tumor and increased expression of VEGF and Dll4, which support the combined use of Ephrin-B2, VEGF, and Dll4 inhibitors." (PMID 21092311, 2010). "Among them, EphB4 and ephrinB2 arbitrate the enhanced proliferation, migration and metastatic potential of tumour cells." (PMID 18231102, 2008). "Overexpression of EphB4 and ephrinB2 in tumour cells suggests that EphB/ephrinB signalling drives destabilisation, which can also affect cell–matrix attachment, and thereby promote invasion and metastasis." (PMID 18231102, 2008).